TMC1 (transmembrane channel like 1)
Diseases named in the same sentence as TMC1 in open-access papers (continued):
Sharing a sentence is not in itself a finding about the gene and the disease.
deafness (continued). "TMC1 has been implicated both in autosomal recessive (DFNB7/11) and autosomal dominant (DFNA36) deafness forms." (PMID 24926664, 2014). "Bi-allelic mutations in 15 less commonly screened deafness genes were identified in 28 deaf probands, with mutations in MYO15A, GPR98, TMC1, USH2A and PCDH15 being relatively more frequent (≥3 probands each)." (PMID 23767834, 2013). "In some populations, including Iran and Turkey, as Israel, TMC1 is one of the genes most frequently involved in deafness." (PMID 21917145, 2011). "For the Israeli deaf population of Moroccan Jewish ancestry, this study has substantial clinical implications, as the TMC1 gene was found to be very frequently involved in deafness in this population." (PMID 21917145, 2011). "Identifying TMC1-related deafness enabled timely cochlear implantation and measurable gains." (PMID 41594276, 2026). "Furthermore, the apparent severity of the mutants, as implied by the time of onset of deafness, is proportional to the degree of reduction in Ca2+ permeability, the Tmc1 p.T416K retaining some hearing function longer than the Tmc1 p.M412K." (PMID 40100636, 2025). "Whether similar kinetics apply to gene editing (e.g., CRISPR-Cas9) or other deafness genes (e.g., Tmc1 and Otof) remains untested." (PMID 40792200, 2025). "Transmembrane channel-like protein 1 (TMC1), a pore-forming component of the mechano-electrical transducer (MET) channel in cochlear outer hair cells, is subject to numerous mutations causing deafness and hair cell death." (PMID 40100636, 2025). "Tmc1 and 2 are mechano-electrical transducer (MET) channels in cochlear hair cells, and mutations in Tmc1/2 cause deafness in humans and mice by disrupting hair cell mechanoelectrical transduction, and Tmc gene therapy can restore auditory function and balance in mice." (PMID 39269275, 2024). "We compare its properties with those of other deafness mutants Tmc1 p.D569N and Tmc1 p.D528N." (PMID 33824189, 2021). "Mutations in the TMC1 and TMC2 cause deafness in humans and mice." (PMID 33193678, 2020). "The mutation in TMC1 gene encoding the transmembrane, channel–like protein isoforms 1 (TMC1) may cause autosomal recessive (DFNB7/11) or dominant (DFNA36) deafness." (PMID 32098144, 2020). "Moreover, the expression levels of the other nine deafness-related genes (Myo15, Gfi1, Lhx3, Barhl1, Pjvk, Tomt, Pou4f3, Tmc1, and Grxcr2) were downregulated more than 2-fold in DT-treated Prestin-hDTR mice." (PMID 30918314, 2019). "The known deafness genes with variants detected in this study were GJB2 (MIM 121011; 21.2%), TMPRSS3 (MIM 605551; 6.1%), MYO15A (MIM 602666; 6.1%), TMC1 (MIM 606706; 3%), ADGRV1 (MIM 602851; 3%), PTPRQ (MIM 603317; 3%), SLC26A4 (MIM 605646; 3%), and OTOF (MIM 603681; 3%)." (PMID 31379920, 2019). "Using zebrafish as a deafness model, Pacentine and Nicolson demonstrate that Tmie is required for the localization of the channel subunits, transmembrane channel-like (Tmc) proteins Tmc1/2b." (PMID 30726219, 2019). "Furthermore, we report that calcium and integrin-binding protein 2 binds to the components of the hair cell mechanotransduction complex, TMC1 and TMC2, and these interactions are disrupted by deafness-causing Cib2 mutations." (PMID 28663585, 2017). "Furthermore, not only N-terminal truncations of CIB2, but also several other deafness-associated missense mutations (p.E64D, p.F91S, and p.C99W), located in the central region of CIB2, also disrupt its interaction with TMC1." (PMID 28663585, 2017). "Of them, three were novel missense mutations (p.G38D in COCH, p.E316K in ACTG1, and p.P164R in POU4F3), one was a novel in-frame indel mutation (c.2036-2038delAGG in WFS1), and two were known deafness-causing mutations that have been previously reported (p.R653C in WFS1 and p.D572N in TMC1)." (PMID 25388789, 2014). "Three of them, p.R2728H in MYO15A, p.R445H and c.150delT in TMC1, have been previously reported to be associated with non-syndromic deafness." (PMID 23767834, 2013).
deafness (continued). "Thus, TMC-1-expressing C. elegans provides a genetically tractable in vivo model to study TMC protein trafficking and to investigate the pathogenic mechanisms of deafness-associated mutations." (PMID 40650136, 2025). "Interestingly, in another mouse model for DFNB7/11 recessive deafness with a defect in Tmc1, round window membrane injections of synthetic AAV2/Anc80L65 encoding Tmc1 resulted in the approximately complete restoration of auditory and vestibular function and morphological rescue." (PMID 33987950, 2021). "Our study expanded the mutation spectrums of TMC1 and MYO15A and illustrated that genotype-phenotype correlation in combination with next-generation sequencing may improve the accuracy for genetic diagnosis of deafness." (PMID 32802042, 2020). "Twelve homozygous mutations in known deafness genes, of which eight are novel, were identified in 12 families: MYO15A-p.Q1425X, -p.S1481P, -p.A1551D; LOXHD1-p.R1494X, -p.E955X; GIPC3-p.H170N; ILDR1-p.Q274X; MYO7A-p.G2163S; TECTA-p.Y1737C; TMC1-p.S530X; TMPRSS3-p.F13Lfs*10; TRIOBP-p.R785Sfs*50." (PMID 23226338, 2012). "TMC1 and TMC2 were initially identified in human deafness patients, and studies have shown that they also play key roles in mice and zebrafish." (PMID 41049429, 2025). "TMC1, another OMIM Morbid gene, whose variation associated with autosomal dominant deafness-36 (DFNA36; OMIM #606705) and autosomal recessive deafness-7 (DFNB7), also known as DFNB11 (OMIM #600974)." (PMID 40692708, 2025). "Those in TMC1, CDH23, LOXHD1 and USH2A were each detected in two probands, and those in 10 other deafness genes were each detected in one proband." (PMID 35062939, 2022). "The transmembrane channel–like 1 (TMC1) protein localizes to the site of the MET channel, interacts with the tip-link responsible for mechanical gating, and genetic alterations in TMC1 alter MET channel properties and cause deafness, supporting the hypothesis that TMC1 forms the MET channel." (PMID 30063209, 2018). "In the present study 53% (16/30) of the families were found to carry causative mutations in GJB2 illustrating that the most frequently involved gene in deafness in the Pakistani population is GJB2 followed by MYO15A (13%, 4/30) and TMC1 (10%, 3/30)." (PMID 24949729, 2014). "TMC1 and TMC2 play a crucial role in the mechanoelectrical transduction of hair cells and may also mediate hair cell damage and apoptosis, leading to deafness, by affecting intracellular Ca2+ homeostasis." (PMID 41049429, 2025). "TMC1 has been identified as the responsible gene for both DFNA36 and DFNB7/B11 deafness." (PMID 26561413, 2015). "Unexpectedly however, we identified compound heterozygous p.L416R/p.A438T mutations of TMC1 in another consanguineous family KLX10, suggesting that the cause of deafness in this family was not originated from the consanguineous marriage." (PMID 26011067, 2015). "The biallelic sequence variants predicted to be the causative mutations in the patients are all located in genes already known to be involved in deafness (MYO15A, TMC1 and LRTOMT), but these particular mutations have not been previously reported." (PMID 24926664, 2014).
hearing loss (53 papers, 2010 to 2026). "Mutations in similar or equivalent pore-lining residues in TMEM16s67–69 and TMEM63B20, have been shown to alter PLS activity, which suggests that the residues altered in these hearing loss-associated mutations play a direct role in TMC1 lipid scrambling." (PMID 40631239, 2025). "Many missense mutations near this disulfide bond in TMC1, including p.P514L, p.C515R, p.C515F, p.P660L, p.C664W, and p.S668R, have been identified and are associated with hearing loss." (PMID 40650136, 2025). "Given the functional correlation between TMC proteins and CIBs in inner ear hair cells, targeted Cib2 gene therapy warrants systematic investigation, with Tmc1’s therapeutic success supporting its potential for treating CIB2-related hearing loss." (PMID 40076845, 2025). "The TMC1 gene was first linked to hereditary hearing loss in 2002, with mutations identified in both human patients and deaf mouse models." (PMID 40650136, 2025). "In 2002, positional cloning following linkage analysis of families with autosomal recessive nonsyndromic deafness (DFNB7/11) led to the discovery of pathogenic mutations in TMC1, causing hearing loss." (PMID 40943399, 2025). "Our data identify the mechanistic basis for this membrane-related hearing loss and indicate that TMC1 and TMC2 can function as both MS channel and lipid scramblases." (PMID 40631239, 2025). "Deafness-causing mutations in TMC1 have been identified in humans, accounting for a significant percentage of inherited hearing loss cases." (PMID 38525683, 2024). "HC-like cells derived from iPSC with TMC1 p.M418K provide a model of hereditary progressive hearing loss in cellular level, which would play an essential role in pathogenesis and therapeutics in an animal-free way." (PMID 38167128, 2024). "Human TMC1 is amongst a cadre of genes subject to pathogenic mutations associated with hearing loss and, thus, an appropriate target for therapeutic intervention." (PMID 38638308, 2024). "Gene suppression involving the use of RNAi (RNA interference) was performed in Beethoven (Bth) mice, a mouse model of TMC1 (transmembrane channel-like 1) autosomal dominant hearing loss." (PMID 38131808, 2023). "Transmembrane channel-like 1 (Tmc1) mutation causes hearing loss, and cationic lipid-mediated in vivo delivery of Cas9:gRNA RNP complex in the humanized transmembrane channel-like 1 (Tmc1) Beethoven (Bth) mouse model ameliorated the pathogenic phenotype." (PMID 37051232, 2023). "TMC1 variants are known to cause autosomal dominant (DFNA36) and autosomal recessive (DFNB7/11) non-syndromic hearing loss, but only a handful of TMC1 variants underlying DFNA36 have been reported, hampering analysis of genotype-phenotype correlations." (PMID 38066485, 2023). "Although this mutation-agnostic approach should be equally applicable to other models of TMC1-related hearing loss, further work is necessary to confirm its broad-based applicability." (PMID 36574989, 2023). "Herein, we report the first use of this strategy in a mature murine model of TMC1-related hearing loss." (PMID 36574989, 2023). "In this study, we retrospectively reviewed 338 probands in an in-house database of genetic hearing loss, evaluating the clinical phenotypes and genotypes of novel TMC1 variants associated with DFNA36." (PMID 38066485, 2023). "Among the 26 probands with TMC1-associated hearing loss, 15 cases were identified from autosomal dominant hearing loss families." (PMID 34523024, 2022). "Similar to previous studies, TMC1-associated ARNSHL patients showed congenital onset severe-to-profound hearing loss, whereas the TMC1-associated ADNSHL patients showed late-onset progressive hearing loss." (PMID 34523024, 2022). "Multiple missense mutations of human CIB2 or TMC-1 are associated with non-syndromic hearing loss by either impeding the interaction between TMC-1 and CIB2 or by reducing the Ca2+ binding propensity of CIB214." (PMID 36224384, 2022).
hearing loss (continued). "A mouse model of TMC1-related hearing loss (Beethoven mice), generated by ENU mutagenesis, showed autosomal dominant inherited progressive hearing loss." (PMID 34523024, 2022). "As a result of the large cohort next-generation sequencing analysis, we identified 26 probands with TMC1-associated hearing loss." (PMID 34523024, 2022). "TMC1-associated ARNSHL cases show congenital severe-to-profound hearing loss, whereas ADNSHL cases show late-onset progressive hearing loss with predominant deterioration in the higher frequencies." (PMID 34523024, 2022). "The prevalence of TMC1-associated hearing loss in other countries is 0.5–8.1% and varies among ethnic populations in the introduction." (PMID 34523024, 2022). "In this study, we identified 26 probands with TMC1-associated hearing loss and the prevalence of TMC1-associated hearing loss in Japanese hearing loss patients was 0.17% for all patients." (PMID 34523024, 2022). "As a result, we identified 26 probands with TMC1-associated hearing loss, with the estimated prevalence of TMC1-associated hearing loss in the Japanese hearing loss cohort being 0.17% among all patients." (PMID 34523024, 2022). "Here, we reported the prevalence of TMC1-associated hearing loss in a large non-syndromic hearing loss cohort of about 12,000 subjects." (PMID 34523024, 2022). "All the affected individuals with recessively inherited TMC1 variants displayed severe-to-profound congenital hearing loss associated with down-sloping audiograms, where higher frequencies are the most severely affected." (PMID 35407445, 2022). "Most cases of TMC1-associated hearing loss are identified as autosomal recessive inherited hearing loss, and only limited cases are identified as autosomal dominant." (PMID 34523024, 2022). "In summary, next-generation sequencing analysis successfully identified 10 previously reported mutations and 7 novel variants for TMC1-associated hearing loss." (PMID 34523024, 2022). "In terms of clinical features, TMC1-associated ARNSHL patients showed congenital onset severe-to-profound hearing loss, whereas the TMC1-associated ADNSHL patients showed late-onset progressive hearing loss." (PMID 34523024, 2022). "Recently, autosomal dominant TMC1-associated hearing loss has received special attention as a candidate for gene therapy." (PMID 34523024, 2022). "We recently described a patient showing hearing loss with an autosomal dominant pattern of inheritance and a pathogenic variant in the TMC1 gene." (PMID 34562878, 2021). "TMC1 mutation was reported to induce both autosomal dominant and recessive hearing loss (DFNA36 and DFNB7/B11) in a large number of populations." (PMID 29692870, 2018). "The auditory phenotypes of the individuals with TMC1 homozygous recessive variants or compound heterozygous variants generally show congenital severe‐profound hearing impairment." (PMID 29654653, 2018). "Between 2002 and 2008, a total of 2 dominant and 18 recessive TMC1 mutations were reported as the cause of hearing loss in 34 families." (PMID 25760145, 2015). "This mutation in TMC1 is orthologous to the mutation found in the hearing loss mouse model named Bth ten years ago." (PMID 24827932, 2014). "TMC1, the transmembrane cochlear-expressed gene 1, was reported as the causative gene for both dominant and recessive hearing loss at the DFNA36 and DFNB7/11." (PMID 24827932, 2014). "Based on their results, Vreugde and colleagues screened the Tmc1 gene and found the p.M412K mutation in a hearing loss mouse model named Bth which was arisen in a large-scale ENU mutagenesis program." (PMID 24827932, 2014). "Our results are in contrast to an NGS study of a different ethnic group, which showed TMC1 mutations to be the prevalent candidate cause of hearing loss." (PMID 24164807, 2013). "TMC1, specifically expressed in the cochlea, encodes a transmembrane channel protein, and is a known gene for hearing loss." (PMID 21917145, 2011).
hearing loss (continued). "We estimate that TMC1 mutations explain at least 38% of inherited hearing loss in the Moroccan Jewish population." (PMID 21917145, 2011). "Mutations in the MYO15A, OTOF, TMC1 and other genes have emerged as being among the more prevalent nonsyndromic hearing loss mutations, worldwide." (PMID 20668687, 2010). "To date, over 90 mutations in TMC1 have been associated with various forms of hearing loss, including DFNA36 (autosomal dominant non-syndromic sensorineural deafness 36), DFNB7/11 (autosomal recessive non-syndromic sensorineural deafness 7/11), and early-onset presbycusis." (PMID 40650136, 2025). "Functional validation is recommended to be carried out in any future study for the variants detected in MYO3A, KCNQ1, PEX6, and TMC1 genes to provide stronger evidence for the pathogenicity of these variants and more robust support for their proposed role in hearing loss." (PMID 40100472, 2025). "In addition, we show that the cholesterol range for optimal TMC1 PLS activity is widened in three different hearing loss-associated TMC1 mutations, enabling these mutant TMC1 proteins to scramble lipids at physiological levels of cholesterol." (PMID 40631239, 2025). "Consequently, TMC1 has emerged as a promising target for gene therapy and gene editing strategies aimed at treating hereditary hearing loss." (PMID 40650136, 2025). "Our group found a large DFNA36 Chinses family with 222 members showing post-lingual, progressive and symmetric sensorineural hearing loss with TMC1 p.M418K mutation which is orthologous to Tmc1 p.M412K mutation found in the Beethoven mouse model decade earlier." (PMID 38167128, 2024). "Alternatively, the varying onset of hearing loss between the two families could be attributed to the variable expressivity of TMC1 variants." (PMID 38066485, 2023). "In most previous studies, TMC1-associated hearing loss was observed more commonly in ARNSHL patients than in ADNSHL patients, and common mutations which may be caused by founder mutation were involved in these cases." (PMID 34523024, 2022). "In conclusion, we suggest that the AAV9-PHP.B-CB6-hTMC1-WPRE vector may be well-suited as a gene therapy reagent for treatment of patients with all forms of recessive TMC1 hearing loss." (PMID 35883470, 2022). "On the other hand, TMC1-associated ADNSHL patients showed late-onset progressive hearing loss." (PMID 34523024, 2022). "The clinical phenotypes of TMC1-associated hearing loss differ according to the inheritance mode." (PMID 34523024, 2022). "When we restricted analysis to Japanese bilateral non-syndromic hearing loss patients, the prevalence of TMC1-associated hearing loss was 0.17% (20/11,594) for all patients, 0.61% (15/2462) for ADNSHL and 0.07% (5/6912) for ARNSHL or sporadic hearing loss cases." (PMID 34523024, 2022). "We conclude that the AAV9-PHP.B-CB6-hTMC1-WPRE construct may be suitable for further development as a gene therapy reagent for treatment of humans with genetic hearing loss due to recessive TMC1 mutations." (PMID 35883470, 2022). "Two pathogenic, one likely pathogenic variants and one SNP of TMC1 were identified in four Chinese families with hereditary hearing loss, indicating that TMC1 may be a more frequent cause of hearing loss than expected." (PMID 29654653, 2018). "In summary, we identified two pathogenic variants, one likely pathogenic variant and one SNP in the TMC1 gene by HTS in four Chinese hearing loss families, including the second report of the p.M412K variant orthologous to that in Bth mice, which are a good model for gene therapy analysis." (PMID 29654653, 2018). "TMC1 variants related to hearing loss result in specific phenotypes." (PMID 29654653, 2018). "The results of gene expression analysis of each cochlear turn showed that 4 ADNSHL genes (Pou4f3, Slc17a8, Tmc1, and Crym) and 9 autosomal recessive non syndromic hearing loss genes (Otof, Strc, Ush1c, Pcdh15, Grxcr1, Dfnb59, Slc26a5, Lhfpl5, and Ptprq) were changed 2-fold or more." (PMID 24676347, 2014).